AXL (AXL receptor tyrosine kinase)
Diseases named in the same sentence as AXL in open-access papers (continued):
Sharing a sentence is not in itself a finding about the gene and the disease.
tumor (continued). "AXL expression is higher in tumor cells than in normal tissues, and it is associated with drug resistance in various cancers." (PMID 33374832, 2020). "AXL is a receptor tyrosine kinase (RTK) that has been implicated in diverse tumor-promoting processes such as proliferation, migration, invasion, survival, and apoptosis." (PMID 32148495, 2020). "AXL, a receptor tyrosine kinase is associated with tumor progression, epithelial‐to‐mesenchymal transition (EMT), and drug resistance, and is a potential therapeutic target." (PMID 31999390, 2020). "GAS6/AXL stimulates multiple pro-tumorigenic signalings associated with tumor progression such as cellular adhesion, invasion, migration, proliferation, and anti-apoptosis." (PMID 31501521, 2020). "By the same token, stratification of patients based on AXL IHC staining of both tumor and immune cells was associated with significantly improved patient survival." (PMID 35582229, 2020). "Activation of AXL was associated with EMT features in erlotinib-resistant tumours and occurred either through its overexpression or via up-regulation of autocrine growth arrest-specific gene 6 (GAS6)." (PMID 32595946, 2020). "AXL expression in the tumor has been implicated in resistance to a variety of therapies, both targeted and conventional, in several different cancer types including breast." (PMID 32148495, 2020). "Sitravatinib has recently been shown to inhibit MET in mesothelioma and lung cancers, PDGFRs in sarcomas, and select TAM (TYRO3, AXL, MerTK) receptors in tumor associated macrophages, amongst several other receptor families." (PMID 31369645, 2019). "Another study in NSCLC patients treated with 1G/2G TKIs or osimertinib found an association between high AXL expression and low RR as well as early tumor progression." (PMID 31266248, 2019). "In cancer, AXL overexpression and activation has been associated with cell proliferation, chemotherapy resistance, tumor angiogenesis, invasion, and metastasis; and has been correlated with a poor prognosis." (PMID 31694201, 2019). "AXL (AXL receptor tyrosine kinase) is associated with EMT in several tumours and its upregulation in the Hedgehog pathway has been recognized as a mechanism of resistance to targeted drugs in EGFR-mutated NSCLC." (PMID 31795465, 2019). "The receptor tyrosine kinase (RTK), AXL, is a key driver of tumor cell EMT and is widely implicated in acquired drug-resistance to multiple cancer drug classes." (PMID 29719832, 2018). "Elevated AXL expression is associated with poor outcome in tumors of the lung, breast, and pancreas." (PMID 29097911, 2017). "For example, upregulation of the receptor tyrosine kinase AXL has been implicated in resistance to TKIs in a number of tumor types." (PMID 29806049, 2017). "Mice injected with AXL-deficient cells developed fewer intraperitoneal metastases and had lower tumor weight than mice injected with AXL-expressing cells." (PMID 27764792, 2016). "While AXL is highly expressed on tumor associated macrophages, the functional role of AXL in these cells remains poorly understood." (PMID 27834845, 2016). "Here we will highlight recent studies that have implicated AXL signaling in tumor proliferation, survival, anti-apoptosis, drug resistance, the stem cell phenotype, metastasis, and immune suppression." (PMID 27834845, 2016). "The ability of AXL signaling to promote tumor growth has been associated with the activation of downstream proliferation and/or survival pathways including MAPK, PI3K/AKT, and FAK/Src/NFKB signaling." (PMID 27834845, 2016). "The receptor tyrosine kinase AXL is over-expressed in different types of cancers and implicated in several malignant phenotypes of tumor cells, such as invasion and chemoresistance." (PMID 27015365, 2016). "We found that AXL expression was significantly elevated in tumor tissues and associated with pathological stage." (PMID 27172793, 2016).
tumor (continued). "In an orthotopic colon model of human HCT116 CRC cells overexpressing AXL, foretinib treatment caused significant inhibition of tumour growth and peritoneal metastatic spreading." (PMID 25966280, 2015). "AXL in particular has been implicated in metastasis in multiple tumor types and facilitates EMT in addition to upregulation of MMP9." (PMID 26328272, 2015). "AXL is also associated with tumor cell invasion and metastasis and promotes tumor growth in various kinds of cancer." (PMID 25780909, 2015). "In fact, AXL overexpression has been associated with tumor cell migration and invasion, epithelial-to-mesenchymal transition (EMT), and poor survival in different types of cancers." (PMID 25593196, 2015). "The other target genes, FLT3, CSF1R, PDGFRB, AXL and MET showed lower expression levels in the tumor tissue compared to normal tissue except AXL in NF1 associated GIST." (PMID 21171987, 2010). "AXL may contribute to the development and progression of ccRCC by interacting with M2 macrophages and participating in tumor malignancy-associated pathways such as EMT." (PMID 41029360, 2025). "Inhibiting AXL enhances the susceptibility of tumour cells to PI3Kα inhibitors via R428." (PMID 40088262, 2025). "AXL exhibits high or ectopic expression in multiple malignant tumors, and this overexpression has been linked to drug resistance in lung, breast, and esophageal cancers, as well as tumor invasion." (PMID 39598398, 2024). "AXL expression is associated with multiple processes in cancer progression, including invasive tumor growth, therapy resistance, a more migratory mesenchymal phenotype, and poor clinical outcomes, and is also expressed on tumor-associated immune and endothelial cells." (PMID 39238637, 2024). "AXL is uniquely associated with both tumor intrinsic and immune resistance mechanisms." (PMID 39238637, 2024). "We found that the detection of AXL+ CTCs was associated with the tumor histological (SBR) grade." (PMID 38132919, 2023). "AXL+ CTC detection was only associated with the tumor histological grade (p = 0.036)." (PMID 38132919, 2023). "Here, AXL expression positively associated with the BL PDAC tumor subtype." (PMID 35993361, 2022). "Building on previous research demonstrating successful tumour inhibition using an AXL-targeting ADC across several AXL expressing tumour types, further research to better characterise the anti-tumour immune response associated with the ADC was undertaken using enapotamab vedotin (EnaV)." (PMID 36046842, 2022). "AXL is overexpressed in tumor tissue of NSCLC patients and associated with poor survival." (PMID 33740988, 2021). "In addition to GAS6, it is shown that tumor-associated microglia produce protein S which subsequently interacts with and activates AXL in mesenchymal GSCs and promotes growth of GBM cells, and inhibition of AXL suppresses the promoted growth of GBM cells." (PMID 34831142, 2021). "Moreover, we also emphasized the role of immunity and found that AXL was significantly associated with tumor microenvironment, immune checkpoint molecules, immune infiltration and TMB." (PMID 34838035, 2021). "Mechanisms underlying this association are likely to be related to the ability of AXL to activate several different signal transduction pathways promoting tumor cell survival, proliferation, migration, and invasiveness as well as epithelial‐to‐mesenchymal (EMT)." (PMID 34877810, 2021). "However, another study showed that MerTK and AXL-deficient mice exhibit exacerbated tumor growth and inflammation associated cancer." (PMID 32802188, 2020). "Indeed, AXL loss has promoted a significant reduction in circulating levels of tumor cells and has reduced their ability to exit blood vessels and colonize distant sites." (PMID 33182542, 2020). "In addition, there was a significant association between the tumor stage and AXL expression as indicated by the Pearson test (p < 0.001)." (PMID 32922529, 2020).
tumor (continued). "In addition, osimertinib trended to cause tumor shrinkage more remarkably in patients with AXL-low expression compared to AXL-high expression (p = 0.094)." (PMID 32929081, 2020). "Our data confirmed this, and in addition, we could show that AXL serum levels are associated with internal tumor load." (PMID 32193699, 2020). "As such, AXL’s aberrant expression/activation are strongly associated with tumor progression." (PMID 33182542, 2020). "Elucidation of the role of PTBP1 in the AXL-related malignant phenotypes may provide new molecular insights into the mechanisms underlying tumor progression and hopefully lead to new potential therapeutic modalities." (PMID 31729427, 2019). "Furthermore, HP1γ-induced downregulation of the LRF/ZBTB7A favors the expression of several tumor-promoting factors, such as AXL receptor tyrosine kinase (AXL), plasmacytoma variant translocation 1 (PVT1), and ETS Like-1 protein (ELK1)." (PMID 31823818, 2019). "Since cancers usually have a high proportion of proliferative cells and are associated with a hypoxic environment, inhibition of tumor growth by AXL/MET inhibitors might decrease their oxygen demand." (PMID 31781483, 2019). "AXL is highly expressed within tumor associated macrophages where AXL may promote immunosuppressive and pre-neoplasia phenotypes." (PMID 29455648, 2018). "AXL signaling is also implicated in tumor growth and survival." (PMID 28247252, 2017). "Furthermore, considering the potential association between AXL expression and tumor immune response, we evaluated the clinical significance of global macrophage content in the internal cohort of TNBC patients." (PMID 28721387, 2016). "Interestingly, AXL overexpression was associated with distant tumor recurrence, particularly to visceral organs, indicating a specific route of tumor dissemination for a subset of these tumors." (PMID 28721387, 2016). "Because several studies implicated AXL in tumor migration, we investigated whether AXL has similar functions in ES." (PMID 25528764, 2014). "Furthermore, evidence suggests that AXL expression in tumor cells is associated with an immunosuppressive phenotype that may be associated with resistance to PD-1 blockade." (PMID 41166388, 2025). "However, whether the expression of AXL on both tumor-associated and normal endothelial cells could lead to systemic toxicities of anti-AXL mAbs has to be considered and explored." (PMID 38510242, 2024). "Upregulation of Gas6/AXL is associated with carcinogenesis in multiple malignancies and shortens overall survival, and may be involved in tumor cell proliferation, migration, apoptosis, and maintenance of tumor stem cells through multiple signaling pathways." (PMID 37265798, 2023). "Moreover, AXL-CAR T cells may modulate the tumour immunosuppression by reducing M2 polarization of tumour-associated macrophages (TAM)." (PMID 36261437, 2022). "AXL expression has been linked to metastasis, treatment resistance and poor survival, thus monitoring the levels of AXL in patients may be a tool to determine if the patient tumors display aggressive tumor characteristics." (PMID 31917795, 2020). "Similarly, AXL-associated tumor inflammation is correlated with poor prognosis in TNBC patients." (PMID 32148495, 2020). "As high AXL expression is linked to a more invasive phenotype, acquiring resistance with this phenotype could lead to a more aggressive state, which could be further supported by the regressing tumour microenvironment." (PMID 28606996, 2017). "Increasing studies have emphasized the important roles of GAS6/AXL in tumor progression and TME reprogramming in multiple malignancies including NSCLC 58, making it an emerging therapeutic target." (PMID 41356185, 2026). "AXL drives drug resistance through diverse mechanisms, including altering tumor cell phenotypes, orchestrating DNA damage response process, promoting the activation of bypass signals, or interacting with other receptor tyrosine kinases." (PMID 41916916, 2026).
tumor (continued). "AXL inhibition significantly delayed tumor regrowth of AXL-overexpressing cells by enhancing HER2-TKI-induced apoptosis in xenograft models." (PMID 41927886, 2026). "Such a treatment strategy is less likely to lead to off-target effects and results from this study lends itself as a platform to study downstream consequences of AXL inhibition within the tumour and the microenvironment." (PMID 40696160, 2025). "GAS 6/AXL signaling pathway plays an essential role in tumor cell survival, migration, proliferation, epithelial–mesenchymal transition (EMT), inhibition of apoptosis and drug resistance, which promising a potential targeted for treatment." (PMID 39644434, 2025). "Further studies to explore the interaction between the additional targets and the STAMBPL1/TRIM21/AXL axis will expand the understanding of the function of STAMBPL1 in tumor progression." (PMID 39527690, 2025). "As a result, this process stimulates the activation of AXL through phosphorylation, leading to the enhanced ability of tumour cells to resist immune-mediated elimination." (PMID 40088262, 2025). "SLC-391, a novel, orally bioavailable and selective AXL inhibitor, has demonstrated potent anti-tumour effects in preclinical studies." (PMID 41471387, 2025). "We identifies WNT-activated tumor-initiating cells evading immune attacks by interacting with macrophages through the GAS6/AXL/MERTK pathway, suggesting new targets for cancer therapy." (PMID 39774471, 2025). "For example, in colorectal cancer, GALNT2 modifies the O-glycosylation of the AXL receptor tyrosine kinase, thereby regulating AXL levels and promoting tumor invasion." (PMID 40861802, 2025). "This method identified key signaling pathways, such as the PDGFR–PTPN11–FOS axis, and regulatory mechanisms like the AXL ectodomain, crucial for tumor progression and immune evasion in PDAC." (PMID 40164585, 2025). "Overexpression or activation of AXL promotes tumor growth, differentiation, proliferation, and metastasis by activating the PI3K/AKT and/or MAPK/ERK pathways." (PMID 40157901, 2025). "AXL also has a regulatory role in the formation of NK cells, which are crucial for the surveillance and eradication of tumour cells." (PMID 40088262, 2025). "Collectively, targeting the STAMBPL1/TRIM21/AXL axis can decrease mesenchymal phenotype and potentiate anti‐tumor efficacy of cancer therapy." (PMID 39527690, 2025). "Our results collectively indicate that targeting AXL using AB-329 improves the tumor immuno-microenvironment by increasing activated NK cells." (PMID 41009462, 2025). "This review primarily focuses on the induction, regulation and biological functions of AXL in mediating these tumor-promoting pathways." (PMID 39924521, 2025). "For example, ADAM12 promotes efferocytosis and polarizes macrophages toward an immunosuppressive M2 phenotype in a tumor microenvironment via an AXL-dependent mechanism involving Gas6 secretion." (PMID 41181101, 2025). "To investigate this, we further analyzed the expression of AXL on several tumor cell lines using these three antibodies." (PMID 40933570, 2025). "In vitro, third-generation AXL-CAR-T cells exposed to AXL-positive cancer cells showed anti-tumor effects through the induction of cytokine production and response to cell death." (PMID 39755633, 2025). "Immune infiltration and spatial transcriptomics analyses further revealed that AXL promotes tumor progression interaction with M2 macrophages." (PMID 41029360, 2025). "These agents aim to block AXL signaling and restore tumor sensitivity to conventional treatments, thereby improving patient outcomes." (PMID 40277909, 2025). "AXL, a member of the TAM family of RTKs, is implicated in activating survival pathways, including RAS/RAF/MAPK and PI3K/Akt/mTOR, which are critical for tumor proliferation and resistance." (PMID 39941857, 2025). "Based on the median AXL expression level, we divided all TCGA-ccRCC tumor samples into high- and low-expression groups." (PMID 41029360, 2025).
tumor (continued). "In AXL‐driven cancer models, pacDNA inhibits AXL signaling and reduces tumor growth, highlighting the promise of precision polymer scaffolds in aptamer‐based cancer therapeutics." (PMID 40566927, 2025). "EGFR undergoes nuclear translocation upon activation of AXL and AXL knockdown facilitates inhibition of tumor proliferation by modulating EGFR activity." (PMID 40560045, 2025). "We showed that AXL expression is positively correlated with monocytes in the MES-dominant tumor samples (cor = 0.48; P = 1.04e-2)." (PMID 39825754, 2025). "Inhibiting AXL not only affects tumour cells but also directly affects the immune system, increasing the ability of immune cells to destroy tumour cells." (PMID 40088262, 2025). "To further validate the biological function of the key gene AXL in the occurrence and development of ccRCC, we first collected tumor tissues from ccRCC patients as well as adjacent normal tissues for PCR and IHC analysis." (PMID 41029360, 2025). "Future research should focus on clarifying AXL’s roles in viral pathogenesis, tumor biology, and related comorbidities, paving the way for innovative treatment strategies." (PMID 39924521, 2025). "First, we analyzed the expression levels of AXL in tumor tissues and normal tissues across various cancers using data from the TCGA and GTEx databases." (PMID 41029360, 2025). "We evaluated the expression of AXL in various single-cell (and single-nucleus) datasets and also detected expression in the tumor microenvironment, especially in MES, immune, and schwann cell compartments." (PMID 39825754, 2025). "AXL is a receptor tyrosine kinase that plays a crucial role in immune regulation and tumor progression." (PMID 40677703, 2025). "First in the tumor cells, where AXL inhibition would disrupt developmental, proliferative, and migratory pathways, and second, in the tumor microenvironment, where MERTK suppression would modulate the innate immune response." (PMID 39924521, 2025). "Further analysis focused on the relationship between AXL expression and immune cell infiltration in tumor tissues." (PMID 41029360, 2025). "This ADC is designed to exploit the overexpression of AXL in tumor cells, allowing for selective targeting and internalization." (PMID 41347223, 2025). "Given their roles in tumor progression, both AXL and ROR2 have emerged as promising targets for CAR-T therapies." (PMID 40677703, 2025). "Pharmacological inhibition of MerTK or AXL, when combined with radiotherapy or chemotherapy, augments the immunogenicity of tumor cell death, increases antigen release, and thereby strengthens adaptive immune activation." (PMID 41403915, 2025). "In different cancer types, AXL is implicated in epithelial-mesenchymal transition (EMT), a critical determinant of tumour cell plasticity." (PMID 40044635, 2025). "These cells express GAS6 stimulating AXL-dependent efferocytosis by tumour macrophages, M2 polarisation, immunosuppression and angiogenesis." (PMID 40044635, 2025). "We present evidence that gilteritinib inhibits cell survival, triggers apoptosis and cell cycle arrest, and reduces cell motility, further suggesting that gilteritinib has therapeutic potential for tumor activity in AXL-positive solid tumor cells." (PMID 40157901, 2025). "Cabozantinib is a multitargeted TKI that inhibits VEGFR, MET, and AXL pathways, which are vital for tumour progression and angiogenesis but also play critical roles in maintaining normal liver function." (PMID 40957947, 2025). "This ADC is designed to exploit the expression profile of AXL in tumor cells to deliver potent cytotoxic agents selectively." (PMID 41347223, 2025). "Elevated AXL levels contribute to immune evasion by increasing PD-L1 expression and promoting the clearance of tumor antigens, thereby limiting effective anti-tumor immune responses." (PMID 40677703, 2025).